CMTM3 (CKLF like MARVEL transmembrane domain containing 3)
Synonyms: CKLFSF3; FLJ31762; BNAS2
Tractability: Antibody: UniProt predicts a signal peptide or a membrane-spanning region. PROTAC: ubiquitination databases record sites on it; its protein half-life has been measured.
Gene: Protein-coding gene on chromosome 16 (66,603,874 to 66,613,892, forward strand). Ensembl gene ENSG00000140931.
Subcellular location: Membrane
Subcellular location (Human Protein Atlas): Nucleoplasm
Gene Ontology:
Molecular function: protein binding
Cellular component: cytoplasmic vesicle; cytosol; membrane; cytoplasm; nuclear membrane
Genetic constraint (gnomAD): Loss-of-function variants: 7 observed, 16.41 expected, observed/expected ratio (o/e) 0.43, 90% interval 0.24 to 0.8. The upper end of that interval is the gene's LOEUF score, 0.8, which puts it in group 3 of 6, group 1 being the genes least tolerant of losing a copy. Missense variants: 227 observed, 222.89 expected, observed/expected ratio (o/e) 1.02, 90% interval 0.91 to 1.14. Synonymous variants: 109 observed, 95.46 expected, observed/expected ratio (o/e) 1.14, 90% interval 0.98 to 1.34.
Homologues: Orthologues: chimpanzee CMTM3 (99% identical), macaque CMTM3 (98% identical), mouse Cmtm3 (88% identical), rabbit CMTM3 (87% identical), dog CMTM3 (85% identical), rat Cmtm3 (83% identical), tropical clawed frog cmtm3 (51% identical), zebrafish cmtm3 (50% identical), Caenorhabditis elegans F28H1.4 (12% identical), Caenorhabditis elegans F47B3.3 (9% identical). Paralogues in human: CMTM5 (33% identical), PLP2 (25% identical), CMTM1 (21% identical), CMTM6 (20% identical), MARVELD1 (19% identical), CMTM4 (18% identical), CMTM2 (16% identical), MALL (15% identical), MAL2 (14% identical), CMTM7 (14% identical), MAL (14% identical), PLLP (14% identical), and 2 more.
Diseases named in the same sentence as CMTM3 in open-access papers:
CMTM3 is named in the same sentence as 39 diseases in open-access papers, as found by Europe PMC text mining. Sharing a sentence is not in itself a finding about the gene and the disease. The quoted sentences say what the papers report.
gastric cancer (15 papers, 2016 to 2025). A primary or metastatic malignant neoplasm involving the stomach. "Our previous results showed that CMTM3 expression is strongly associated with gender, tumor depth, stage, and histological grade in 350 gastric cancer samples." (PMID 27121055, 2016). "Although Helicobacter pylori (H. pylori) infection is a main cause of gastric cancer, the function of CMTM3 during H. pylori infection remains unclear." (PMID 36782312, 2023). "CMTM3 has been reported defective in gastric cancer, and overexpression of CMTM3 inhibited cell migration mediated by EGF signaling." (PMID 39948411, 2025). "In gastric cancer, CMTM3 promotes the degradation of EGFR to impede tumor metastasis, indicating that knocking out the CMTM3 gene can be a potential therapy for gastric cancer." (PMID 38223763, 2024). "The CMTM3 gene is a novel gastric cancer suppressor gene that restrains cell migration and invasion." (PMID 36782312, 2023). "Many studies have demonstrated that CMTM3 contributes to cancers and acts as a gastric cancer suppressor." (PMID 36782312, 2023). "It is reported that miR-135b-5p is dysregulated, including gastric cancer cells and tissues, which promotes gastric cancer progression and metastasis through inhibiting CMTM3 expression." (PMID 34277424, 2021). "Our previous study showed that CMTM3 was downregulated in gastric cancer patients and gastric cancer cells, and acted as a tumor suppressor in gastric cancer development." (PMID 34560882, 2021). "CMTM3 was identified to regulate the migration and invasion of gastric cancer cells and thought to be a clinical candidate marker for determining the prognosis of gastric cancer." (PMID 33585698, 2021). "Our previous data also demonstrated that CMTM3 suppressed the metastasis of gastric cancer through the EGFR/STAT3/EMT signaling pathway by interacting with Rab5." (PMID 34560882, 2021). "Knockdown of CMTM3 promoted metastasis of gastric cancer via the STAT3/Twist1/EMT signalling pathway." (PMID 29213215, 2017). "Restoration of CMTM3 significantly inhibits the metastasis of gastric cancer, and its expression level is correlated with prognosis." (PMID 27121055, 2016). "Our results showed that out of these proteins, only Twist1 is involved in the CMTM3-suppressed EMT phenotype in gastric cancer cells." (PMID 27121055, 2016). "CMTM3 expression is reduced or silenced by methylation in gastric cancer cell lines and in primary gastric cancer tissues." (PMID 27121055, 2016). "Restoration of CMTM3 inhibits the migration and metastasis of gastric cancer cells in vitro and in vivo." (PMID 27121055, 2016). "Our previous study showed that CMTM3 is silenced or downregulated in gastric cancer cell lines and in primary gastric cancer tissues." (PMID 27121055, 2016). "Combined with the in vitro findings, we conclude that the knockdown of CMTM3 promotes cell migration, invasion and metastasis of gastric cancer cells." (PMID 27121055, 2016). "The prognosis of gastric cancer patients whose tumors express CMTM3 is better than those whose tumors lack CMTM3 expression." (PMID 27121055, 2016). "Earlier studies have indicated that CMTM3 is downregulated or silenced in gastric cancer cell lines and in primary tumor tissues." (PMID 27121055, 2016). "Here, we suppress CMTM3 expression by shRNA to explore its endogenous effects and its mechanism of action in gastric cancer." (PMID 27121055, 2016). "Overall, this study demonstrates that knockdown of CMTM3 promotes the metastasis of gastric cancer through the STAT3/Twist1/EMT pathway." (PMID 27121055, 2016). "In summary, our data demonstrate that CMTM3 suppresses gastric cancer metastasis via the STAT3/Twist1/EMT pathway, which will be helpful in our understanding of the pathogenesis of gastric cancer and provide novel clues for the early diagnosis of metastasis." (PMID 27121055, 2016). "Taken together, knockdown of CMTM3 promoted cell migration though the STAT3/Twist1/EMT pathway in gastric cancer." (PMID 27121055, 2016).
gastric cancer (continued). "In this paper, we investigated the effects and the mechanism of endogenous CMTM3 in human gastric cancer cells using lentiviral short hairpin RNA (shRNA)." (PMID 27121055, 2016). "Although the link between H. pylori infection and gastric cancer is established, the role of CMTM3 during H. pylori infection is unknown." (PMID 36782312, 2023). "However, the role of CMTM3 during H. pylori infection, representing an early stage in the development of gastric cancer, is unclear." (PMID 36782312, 2023). "Our previous study demonstrates that CMTM3 suppresses metastasis of gastric cancer through the STAT3/EMT signaling pathway by interacting with Rab5 to facilitate EGFR degradation and CMTM3 may serve as a prognostic and predictive biomarker in gastric cancer." (PMID 34560882, 2021). "Our previous studies found that CMTM3 participated in EMT in gastric cancer cells." (PMID 34560882, 2021). "Moreover, CMTM3 exhibits tumor-suppressor roles in cancer progression, including testicular cancer, oral squamous cell carcinoma and gastric cancer." (PMID 34560882, 2021). "In addition, miR-135b-5p regulated cell metastasis and epithelial-mesenchymal transition (EMT) in gastric cancer by targeting CKLF-like MARVEL transmembrane domain containing 3 (CMTM3)." (PMID 33726823, 2021). "It is therefore necessary to further determine other upstream activators of the STAT3/Twist1/EMT pathway in the CMTM3-knockdown system and to investigate the function of CMTM3 on the expression, stabilization, internalization and degradation of RTKs in gastric cancer cells." (PMID 27121055, 2016). "In this study, the inhibitory effects of CMTM3 on EMT in gastric cancer may extend our understanding of the function of the CMTM family and MARVEL-related proteins on EMT during carcinogenesis." (PMID 27121055, 2016). "In addition, CMTM3 reduced the phosphorylation of ERK1/2 in gastric cancer cells." (PMID 34560882, 2021). "However, the physiological effects and the mechanism of CMTM3 in the metastasis of gastric cancer remain unknown." (PMID 27121055, 2016). "CMTM3 affects EMT progression by inhibiting the EGFR/STAT3 signaling pathway, thereby inhibiting the development of tumorigenesis in chordoma and gastric cancer." (PMID 38223763, 2024). "The gastric cancer cell lines AGS and SGC-790 are defective in CMTM3 gene expression, as compared with that in normal tissue." (PMID 32944388, 2020). "In the gastric cancer cell lines GES-1, AGS, and SGC-790167, overexpression of CMTM3 results in downregulation of the epithelial protein E-cadherin but upregulation of mesenchymal proteins such as N-cadherin, vimentin, and MMP-2." (PMID 32944388, 2020). "We found that knockdown of CMTM3 promoted cell migration, invasion and tumor metastasis via the STAT3/Twist1/EMT pathway, which will be helpful to understand the pathogenesis of gastric cancer." (PMID 27121055, 2016). "Based on the findings of the current study, it is necessary to analyze the relationship among CMTM3, p-STAT3, Twist1 expression and metastasis in gastric cancer." (PMID 27121055, 2016). "CMTM3 and CMTM5, which have 42% homology and contain a typical CpG island, generally tend to be regarded as tumor suppressors because of their low expression in gastric cancer, prostate cancer, and HCC." (PMID 40179060, 2025). "Our previous studies revealed that CMTM3 inhibited cell migration, but did not affect cell proliferation in epithelial-derived gastric cancer." (PMID 34560882, 2021). "High expression of CMTM3 might correlate with favorable prognosis in gastric cancer, which not only inhibits the EGF-mediated tumorigenicity by promoting Rab5 activity, but also suppresses metastasis of gastric cancer via the STAT3/Twist1/EMT pathway." (PMID 33282744, 2020).
pancreatic cancer (7 papers, 2019 to 2025). "In a recent paper on tumor cell proliferation and migration, the author found that over-expression of CMTM3 was associated with low pathological grade, high recurrence/metastasis rate, and worse survival in pancreatic cancer." (PMID 35252165, 2022). "However, the expression of CMTM3 in pancreatic cancer is unknown and the association between CMTM3 expression and the prognosis and clinicopathological features of PC patients remains unclear." (PMID 34475993, 2021). "While CMTM3 overexpression has been shown to promote proliferation in pancreatic cancer, it can also inhibit human testicular cancer cell growth." (PMID 39195242, 2024). "Increased expression of CMTM3 in pancreatic carcinoma was correlated with lower pathological grade, higher recurrence/distant metastasis rate, and poorer survival time." (PMID 36975415, 2023). "Some studies have demonstrated that the overexpression of CMTM3 in pancreatic carcinoma was correlated with high recurrence, distant metastasis rate, low pathological grade, and poor survival times." (PMID 36975415, 2023). "In the current study, we observed that CMTM3 was proportionally overexpression in pancreatic cancer tissues and identified the effects of CMTM3 restoration on PC cells proliferation and migration and invasion in vitro." (PMID 34475993, 2021). "However, in pancreatic cancer, CMTM3 promotes cell proliferation and migration and plays a tumor-promoting role." (PMID 40179060, 2025). "However, the previous study also demonstrated that CMTM3 was overexpressed in pancreatic cancer." (PMID 35619698, 2022).
prostate carcinoma (6 papers, 2014 to 2025). A carcinoma that arises from epithelial cells of the prostate gland. "The expression of CMTM3 was decreased in several cancers, such as prostate cancer, and hepatic carcinoma." (PMID 35619698, 2022). "In prostate cancer cells, CMTM3 expression is decreased by IL-30 (134-fold), which has been shown to have pro-tumor activities." (PMID 27121055, 2016). "Previous studies indicated that CMTM3 was silenced or down-regulated in gastric, breast, nasopharyngeal, esophageal, colon and renal carcinomas and its expression inversely correlates with grade and phase in prostate cancer when combined with IL30 study 23-25." (PMID 34475993, 2021). "Compared with the high expression of CMTM3 in normal human testis tissues, the expression of CMTM3 was silenced in a seminoma cell line (NCCIT) and down-regulated or silenced in 2 of 4 prostate cancer cell lines, 2 of 3 renal cancer cell lines and in none of the bladder tumor cell lines studied." (PMID 24586462, 2014).
glioma (5 papers, 2019 to 2025). A benign or malignant brain and spinal cord tumor that arises from glial cells (astrocytes, oligodendrocytes, ependymal cells). "CMTM3 could be used as a potential prognostic biomarker of glioma, which is associated with immune invasion in the glioma microenvironment and may become a new immunotherapy target." (PMID 35619698, 2022). "The result indicated that the levels of CMTM3, CMTM6, CMTM7, CMTM8, and CKLF were much higher in IDH-WT than in IDH-mutated gliomas in the TCGA database (p < 0.001)." (PMID 35252165, 2022). "In high-grade gliomas, RYR2, MCHR2, FADS6, HTR2C, CMTM3, APH1A, and PFN1 genes are related to membrane function." (PMID 37239411, 2023). "As illustrated, the expression of CMTM3, CMTM6, CMTM7, CMTM8, and CKLF in Grade II and III gliomas showed similar tendency as that in TCGA and CGGA databases." (PMID 35252165, 2022). "Results showed that the expression level of CMTM1, CMTM3, CMTM6, CMTM7, CMTM8, and CKLF was elevated in high-grade gliomas (grade III; p < 0.01)." (PMID 35252165, 2022). "In addition, the expression of CMTM3 was positively correlated with macrophages, dendritic cells, and CD4 + T cells in grade II and III gliomas." (PMID 40179060, 2025).
hepatocellular carcinoma (5 papers, 2020 to 2025). A malignant tumor that arises from hepatocytes. "Recent research hinted at the relationship between CMTM3 and PPARγ, whereby the pro-tumorigenic effects of CMTM3 in hepatocellular carcinomas involve the modulation of PPARγ." (PMID 40697995, 2025). "Several members, such as CMTM3, CMTM4, CMTM5 and CMTM7, have been documented to exhibit tumor suppressor functions in hepatocellular carcinoma cells." (PMID 33101541, 2020).
testicular cancer (4 papers, 2014 to 2024). A primary or metastatic malignant neoplasm that affects the testis. "As epigenetic regulation is involved in the expression of CMTM3, we asked whether CMTM3 promoter DNA methylation is associated with a corresponding reduction in CMTM3 expression in testicular cancers." (PMID 24586462, 2014). "Here, we investigated the regulation of CMTM3 expression, function and molecular mechanism in human testicular cancer cells." (PMID 24586462, 2014). "CMTM3 was frequently downregulated or silenced in testicular cancer cell lines and tumor tissues but highly expressed in normal testis tissues." (PMID 24586462, 2014). "The re-expression of CMTM3 significantly suppressed the colony formation, proliferation, and migration capacity of testicular cancer cells by inducing a G2 cell cycle arrest and apoptosis." (PMID 24586462, 2014). "CMTM3 is thus involved in testicular cancer pathogenesis, and it is frequently at least partially silenced by the methylation of a single, specific CpG site in tumor tissues." (PMID 24586462, 2014). "In this study, we observed that CMTM3 was frequently down-regulated in testicular cancer tissues via methylation at a specific, single CpG site located within the Sp1/Sp3-responsive region of the promoter." (PMID 24586462, 2014). "CMTM3 mRNA levels were silenced or strongly downregulated in 16 of 20 testis cancer cases with an overall 5-fold decrease compared to the corresponding benign adjacent tissue (P = 0.002)." (PMID 24586462, 2014). "CMTM3 suppresses the proliferation, and migratory capacity of testicular cancer cells." (PMID 27121055, 2016). "The silencing of CMTM3 in testicular cancer indicated that CMTM3 might be a functional tumor suppressor in testicular carcinogenesis." (PMID 24586462, 2014). "CMTM3 is highly expressed in normal testes, but its role in testicular cancer remains elusive." (PMID 24586462, 2014). "In the present study, we found that CMTM3 was frequently downregulated or silenced in testicular cancer cell lines and primary tumors.We further performed functional studies in NCCIT cells to unveil the biological function of CMTM3." (PMID 24586462, 2014).